KIF22 (kinesin family member 22)
Description:
Kinesin family member that is involved in spindle formation and the movements of chromosomes during mitosis and meiosis. Binds to microtubules and to DNA (By similarity). Plays a role in congression of laterally attached chromosomes in NDC80-depleted cells.
Synonyms: KID; KNSL4; OBP-1; OBP-2; A-328A3.2; OBP; SEMDJL2
Tractability: Small molecule: a structure with a bound ligand is known; it has a binding pocket of medium quality. PROTAC: UniProt records ubiquitination sites on it; ubiquitination databases record sites on it.
Target class: Other cytosolic protein
Gene: Protein-coding gene on chromosome 16 (29,790,718 to 29,805,388, forward strand). Ensembl gene ENSG00000079616.
Subcellular location: Nucleus; Cytoplasm, cytoskeleton
Subcellular location (Human Protein Atlas): Nuclear speckles
Pathways (Reactome):
Hemostasis: Kinesins
Immune System: MHC class II antigen presentation
Vesicle-mediated transport: COPI-dependent Golgi-to-ER retrograde traffic
Gene Ontology:
Molecular function: protein binding; DNA binding; microtubule motor activity; ATP binding; microtubule binding
Biological process: metaphase chromosome alignment; mitotic metaphase chromosome alignment; sister chromatid cohesion; mitotic cell cycle; DNA repair; microtubule-based movement
Cellular component: mitotic spindle; nuclear speck; cytosol; kinesin complex; kinetochore; nucleus; chromatin; cytoskeleton; spindle
Genetic constraint (gnomAD): Loss-of-function variants: 59 observed, 71.51 expected, observed/expected ratio (o/e) 0.83, 90% interval 0.67 to 1.02. The upper end of that interval is the gene's LOEUF score, 1.02, which puts it in group 4 of 6, group 1 being the genes least tolerant of losing a copy. Missense variants: 792 observed, 838.55 expected, observed/expected ratio (o/e) 0.94, 90% interval 0.89 to 1. Synonymous variants: 382 observed, 329.86 expected, observed/expected ratio (o/e) 1.16, 90% interval 1.06 to 1.26.
Homologues: Orthologues: chimpanzee KIF22 (99% identical), macaque KIF22 (96% identical), pig KIF22 (92% identical), dog KIF22 (90% identical), guinea pig KIF22 (82% identical), mouse Kif22 (82% identical), rat Kif22 (81% identical), zebrafish kif22 (50% identical). Paralogues in human: KIF21B (28% identical), KIF21A (27% identical), KIF7 (27% identical), KIF4A (27% identical), KIF4B (27% identical), KIF27 (26% identical), CENPE (24% identical), KIF15 (24% identical), KIF1A (23% identical), KIF19 (23% identical), KIF16B (23% identical), KIF13B (23% identical), and 29 more.
Diseases named in the same sentence as KIF22 in open-access papers:
KIF22 is named in the same sentence as 35 diseases in open-access papers, as found by Europe PMC text mining. Sharing a sentence is not in itself a finding about the gene and the disease. The quoted sentences say what the papers report.
breast carcinoma (7 papers, 2010 to 2024). "Studies have revealed that KIF22 was overexpressed in many cancers, such as lung cancer, gastric cancer, breast cancer, and prostate cancer, and was associated with poor prognosis." (PMID 38713252, 2024). "As FOXA1 had the most significant gene expression, we checked the correlation between FOXA1 and other diabetes-related genes such as PAK4, FGFR3, MTA3, and KIF22 using a database containing 3262 ER+/PR+ breast cancer patient tissue samples." (PMID 39000600, 2024). "Among the diabetes-related genes, FOXA1, MTA3, PAK4, FGFR3, and KIF22 were highly expressed in HR+ breast cancer from 4032 breast cancer patient tissue samples using the Breast Cancer Gene Expression Omnibus." (PMID 39000600, 2024). "KIF22 is abnormally expressed in cervical cancer, ovarian cancer, breast cancer, lung cancer, and prostate cancer." (PMID 35578724, 2022). "A previous research reported that KIF22 was up-regulated in breast cancer and its inhibition could significantly suppress cell proliferation." (PMID 34257566, 2021). "Knocking down of KIF2C, KIF3C, KIF22, KIF18A and KIF24 inhibited proliferation of breast cancer cells via different mechanisms including G2/M phase arrest, delayed exit from mitosis, deregulating cell division and restoring ciliation." (PMID 32322170, 2020). "In human breast cancer cells stably transfected with SIAH-1, Kid/KIF22 protein level was markedly reduced whereas, the Kid/KIF22 mRNA level was increased." (PMID 20144232, 2010). "Five of the 14 diabetes-related genes, FOXA1, KIF22, PAK4, MTA3, and FGFR3, were specifically highly expressed in only the ER+/PR+ and ER+/PR− subtypes but not ER−/PR+ and ER−/PR− through an analysis using 4032 patient tissue samples from Breast Cancer Gene Expression Miner v4.5." (PMID 39000600, 2024).
spondyloepimetaphyseal dysplasia (7 papers, 2018 to 2024). An osteochondrodysplasia that results in abnormalities of bone growth in the vertebral column, epiphysis, and metaphysis. "Whole-exome sequencing associates missense mutations of a kinesin family member, KIF22, with an autosomal-dominant skeletal dysplasia called Spondyloepimetaphyseal dysplasia with joint laxity." (PMID 31636894, 2019). "Note that KIF22-associated spondyloepimetaphyseal dysplasia with joint laxity type 2 is also characterized by spinal deformities, so that additive or epistatic interactions between 16p11.2 genes could contribute to heterogeneity in skeletal phenotypes." (PMID 39332410, 2024). "Heterozygous mutations in the KIF22 gene could cause spondyloepimetaphyseal dysplasia with joint laxity (SEMDJL), which is an autosomal-recessive skeletal dysplasia characterized by short stature, generalized joint laxity, slender hands, limb malalignment, and spinal deformity." (PMID 39039444, 2024).
prostate carcinoma (6 papers, 2017 to 2024). A carcinoma that arises from epithelial cells of the prostate gland. "KIF22 is highly expressed in breast, ovarian, lung, and prostate cancers wherein it is associated with a worse prognosis." (PMID 38989461, 2024). "In prostate cancer, the high expression of KIF22 was involved in tumor progression and adverse clinical outcome." (PMID 38713252, 2024).
gastric cancer (4 papers, 2021 to 2024). A primary or metastatic malignant neoplasm involving the stomach. "Mechanically, KIF22 was reported to promote proliferation and migration in gastric cancer by regulating the MAPK–ERK pathway." (PMID 38713252, 2024). "KIF22 is involved in the migration and proliferation of gastric cancer cells through MAPK-ERK pathways." (PMID 34131588, 2021). "In addition, the abnormally overexpressed KIF22 in gastric cancer tissues is remarkably related to the poor prognosis of gastric cancer patients and silencing KIF22 can reduce the proliferation of gastric cancer cells." (PMID 37944197, 2023).
glioma (4 papers, 2022 to 2025). A benign or malignant brain and spinal cord tumor that arises from glial cells (astrocytes, oligodendrocytes, ependymal cells). "Mechanistically, GBP2 directly interacts with kinesin family member 22 (KIF22) and regulates glioma progression through KIF22/epidermal growth factor receptor signaling in vitro and in vivo." (PMID 41181145, 2025). "Regarding the mechanism, we clarify that EGFR signaling was regulated by GBP2, and also demonstrated that GBP2 directly interacted with KIF22 and regulated glioma progression through KIF22/EGFR signaling." (PMID 35436989, 2022). "This work showed that GBP2 promoted proliferation and migration in glioma cells by regulating EGFR signaling pathway through interactions with KIF22." (PMID 35436989, 2022). "We employed knockdown and overexpression strategies, and the results of in vitro and in vivo assays were highly consistent in demonstrating the function of GBP2 and KIF22 as oncogenes in glioma." (PMID 35436989, 2022). "For example, GBP2 accelerated the proliferation and migration of glioma via KIF22/EGFR pathway." (PMID 37622120, 2023). "Impaired migration ability was also rescued by KIF22 overexpression in both glioma cell lines." (PMID 35436989, 2022). "Similarly, our study indicated that silencing the KIF22 significantly suppressed the progression of glioma progression, and also impaired the protein expression and phosphorylation of EGFR." (PMID 35436989, 2022). "Regarding the mechanism, we clarify that epidermal growth factor receptor (EGFR) signaling is regulated by GBP2, and also demonstrate that GBP2 interacts directly with kinesin family member 22(KIF22) and regulates glioma progression through KIF22/EGFR signaling in vitro and in vivo." (PMID 35436989, 2022). "In this work, we identified GBP2/KIF22/EGFR as a potential therapeutic target for glioma." (PMID 35436989, 2022). "The cell cycle analysis showed that knockdown of KIF22 blocked glioma cells at G0/G1 phase." (PMID 35436989, 2022). "Furthermore, to confirm whether GBP2 promoted the glioma progression by KIF22, we overexpressed KIF22 in GBP2 knockdown cells." (PMID 35436989, 2022). "In summary, we clarified the oncogenic role of GBP2 in glioma and elucidated for the first time the GBP2/KIF22/EGFR pathway in glioma progression." (PMID 35436989, 2022). "As the co-IP results indicated, GBP2 could interact with KIF22 in glioma cells, but not DDX31 and YTHDF2." (PMID 35436989, 2022).
esophageal squamous cell carcinoma (3 papers, 2023 to 2024). Esophageal squamous cell carcinoma (ESCC) is a type of esophageal carcinoma (EC) that can affect any part of the esophagus, but is usually located in the upper or middle third. "KIF22 was pre-transcriptionally regulated by miR-122 in esophageal squamous cell carcinoma cells." (PMID 38713252, 2024). "Recent research suggests that the Kinesin Family Member 22 (KIF22)/miR-122 axis might serve as a biomarker for esophageal squamous cell carcinoma (ESCC) by reducing miR-122 levels, inhibiting the KIF22-mediated growth of ESCC cells." (PMID 36803831, 2023).
lung carcinoma (3 papers, 2022 to 2025). "Four other genes involved in the ceRNA network, including MCM7, NCAPG2, SETD6, and KIF22 have also been reported to involved in lung cancer progression." (PMID 37098483, 2023). "Furthermore, researchers reported that KIF22 can influence the biological processes of phosphorylation for epidermal growth factor receptor (EGFR), which can weaken EGFR internalization and promote EGF-dependent lung cancer cell proliferation." (PMID 35578724, 2022).
colon cancer (2 papers, 2022). "KIF22 may be involved in the regulation of cell proliferation in colon cancer." (PMID 36140838, 2022).
diabetes (2 papers, 2021 to 2024). "We found that KIF22 was significantly associated with age, history of diabetes, alcohol history and neoplasm_histologic grade, while PYGL was markedly correlated with neoplasm_histologic grade (p < 0.05)." (PMID 34257566, 2021). "Herein, we found that KIF22 was significantly associated with history of diabetes." (PMID 34257566, 2021). "Other diabetes-related genes, such as FGFR3, MTA3, PAK4, and KIF22, had similar results." (PMID 39000600, 2024).
ovarian carcinoma (2 papers, 2021 to 2022). A malignant neoplasm originating from the surface ovarian epithelium. "In further studies, whole cell lysates from a series of ovarian cancer cell lines were subjected to immunoblotting for CHFR and some of its substrates, including Aurora A and KIF22." (PMID 34885153, 2021).
pancreatic cancer (2 papers, 2022 to 2024). "Using bioinformatic analysis, we discovered that kinesin family member 22 (KIF22) is highly expressed in pancreatic cancer and that upregulation of KIF22 is associated with a poor prognosis in pancreatic cancer patients." (PMID 35578724, 2022). "Following that, we investigated the role of KIF22 in pancreatic cancer, investigated the effect of KIF22 on pancreatic cancer development, and explored the underlying molecular mechanisms." (PMID 35578724, 2022). "It was finally proven that KIF22 can participate in the cycle regulation of pancreatic cancer cells via the MEK/ERK/P21 signaling axis, thereby promoting the occurrence and progression of pancreatic cancer." (PMID 35578724, 2022). "First, we used the GEPIA database and tissue qRT-PCR to examine the expression of KIF22 mRNA in pancreatic cancer." (PMID 35578724, 2022). "According to our findings, KIF22 is highly expressed in pancreatic cancer and demonstrates a poor clinical prognosis." (PMID 35578724, 2022). "MTT and colony formation experiments revealed that silencing the expression of KIF22 in pancreatic cancer cells significantly reduced cell proliferation ability, including decreased proliferation rate and decreased cell colony formation ability." (PMID 35578724, 2022). "Silencing KIF22 in pancreatic cancer cells significantly reduces cell proliferation ability, demonstrating that KIF22 can promote the occurrence and progression of pancreatic cancer." (PMID 35578724, 2022). "Meanwhile, immunohistochemistry revealed the presence of KIF22 in 71 pancreatic cancer tissues versus 30 paracarcinoma tissues." (PMID 35578724, 2022). "In this study, we found that KIF22 was highly expressed in pancreatic cancer tissues, and patients with high expression of KIF22 demonstrated significantly worse clinical prognosis outcomes (P < 0.05)." (PMID 35578724, 2022). "When the KIF22 gene was silenced in pancreatic cancer cells (PANC-1 and MIA PaCa-2), the cells' ability to proliferate was significantly reduced." (PMID 35578724, 2022). "KIF22 is involved in the cycle regulation of pancreatic cancer cells, according to GSEA and verification." (PMID 35578724, 2022). "This study demonstrates that KIF22 promotes the occurrence and development of pancreatic cancer, and it confirms that its cancer-promoting effect is potentially related to the MEK/ERK/P21 signaling axis." (PMID 35578724, 2022). "To explore the mechanism of KIF22 promoting the occurrence and development of pancreatic cancer, we analyzed the pathway of KIF22 enrichment through GSEA and found that it was highly enriched in the cell cycle regulation pathway." (PMID 35578724, 2022). "The study is aimed at exploring the potential biological process and molecular mechanism of KIF22 involved in the development and progression of pancreatic cancer." (PMID 35578724, 2022). "We discovered that KIF22 was abnormally overexpressed in pancreatic cancer tissue using the GEPIA database, qRT-PCR in fresh tissues, and immunohistochemical staining in pathological sections in this study." (PMID 35578724, 2022). "The results also showed that after silencing KIF22 expression in pancreatic cancer cells, the proportion of cells in the G2/M phase decreased significantly, while the proportion of cells in the G1/S phase increased significantly, inducing G1/S phase arrest (P < 0.05)." (PMID 35578724, 2022). "Furthermore, GSEA confirmed that KIF22 is involved in cell cycle regulation in pancreatic cancer patients (FDR = 0.00158, P < 0.0001)." (PMID 35578724, 2022). "Furthermore, in pancreatic cancer cells, we silenced KIF22 by transfecting KIF22 SiRNA, and we investigated the effect of KIF22 on the proliferation of pancreatic cancer cells with MTT and colony formation assays." (PMID 35578724, 2022). "As a result, we hypothesized that KIF22 may be involved in the occurrence and development of pancreatic cancer." (PMID 35578724, 2022).
pancreatic cancer (continued). "Furthermore, high expression of KIF22 was correlated with a high level of CA199 in serum, an advanced tumor stage, and an unfavorable prognosis in pancreatic cancer." (PMID 35578724, 2022). "As a result, KIF22-targeting inhibitors may be used as adjuncts to MEK-ERK inhibitors to increase drug sensitivity and reduce biotoxicity, slow pancreatic cancer progression, reduce postoperative recurrence rate, and improve pancreatic cancer patients' survival outcomes." (PMID 35578724, 2022). "However, no reports exist on the research of KIF22 in pancreatic cancer." (PMID 35578724, 2022).
tongue squamous cell carcinoma (2 papers, 2023 to 2025). A squamous cell carcinoma that arises from the tongue. "Liu and colleagues have reported that KIF22 is significantly elevated in the tissues of tongue squamous cell carcinoma, and KIF22 inhibition notably restrains the proliferation of cancer cells both in vitro and in vivo." (PMID 37944197, 2023).
cervical adenocarcinoma (1 paper, 2022). An adenocarcinoma arising from the cervical epithelium. "To assess the effect of published pathogenic mutations in the motor domain and the novel pathogenic mutation in the tail on the function of KIF22 in mitosis, we generated human cervical adenocarcinoma (HeLa-Kyoto) cell lines with inducible expression of KIF22-GFP." (PMID 35730929, 2022).
endometriosis (1 paper, 2025). The growth of functional endometrial tissue in anatomic sites outside the uterine body. "In contrast, some genes were significantly downregulated in endometriosis patients, among others KIF22, KIF25, GAS2L2, and HINT3." (PMID 41516028, 2025). "Furthermore, the identification of upregulated genes, such as SIRT1, SBDS, SRF, SPN, P2RX1, TEAD3, and SLITRK3, alongside downregulated genes, including KIF22, KIF25, GAS2L2, and HINT3, highlights a broad transcriptional reprogramming within endometriosis-affected tissues." (PMID 41516028, 2025).